LGR5 (leucine rich repeat containing G protein-coupled receptor 5)
Diseases named in the same sentence as LGR5 in open-access papers (continued):
Sharing a sentence is not in itself a finding about the gene and the disease.
colon carcinoma (continued). "In the present study, we aimed to validate the single biomarkers CD44 rs8193 C>T, ALCAM rs1157 G>A and LGR5 rs17109924 T>C based on our preliminary findings in a large and independent study cohort of 742 stage II and III colon cancer patients." (PMID 25665511, 2015). "Thus, REG4 and LGR5 may contribute independently to the tumorigenicity of colon cancer cells." (PMID 26387746, 2015). "We further have previously shown that miR-363 expression is reduced in colon tumors and that its downregulation results in an increase in GATA6 expression, which thereby enhances LGR5 expression." (PMID 26387746, 2015). "Our findings suggest that GATA6 simultaneously induces the expression of genes essential for colon cancer cell growth under adherent conditions (REG4) and genes that promote their clonogenicity (LGR5)." (PMID 26387746, 2015). "LGR5 belongs to the GPCR family and is a target gene of Wnt signaling that regulates tumorigenesis in colon cancer." (PMID 24789370, 2014). "Commonly repressed genes included the colon and colon cancer stem cell genes ASCL2 and LGR5 as well as EPHB2, SOX4 and P21, all as compared with control cells after normalization with housekeeping genes." (PMID 24920608, 2014). "We also observed, in agreement with previous reports in humans, an overexpression of LGR-5 in macroscopic tumours (i.e. the adenomas), confirming overexpression of the LGR-5 gene that we previously reported in DMH-induced colon tumours." (PMID 23374535, 2013). "CD133+ colon cancer cells include EpCAM hi/CD44+ cells, whereas the relationship between CD133+ subset and Lgr5+ subset is unclear." (PMID 19583834, 2009). "Here we demonstrate that high iron diet augments the regenerative capacity of Hopx+ intestinal stem cells (ISCs) rather than Lgr5+ ISCs to functionally contribute to colon tumor formation." (PMID 42157941, 2026). "In a metastatic murine model of colon cancer, treatment with an anti-EREG antibody induced antitumor activity against tumors derived from EREG-expressing LGR5-positive cells, thereby suggesting that targeting EREG is effective in defeating cancer stemness and chemoresistance." (PMID 38398101, 2024). "Using colon cancer spheroidcultures of primary colorectal cancers and liver metastases, Vermeulen and coworkerswere able to show in 2008 that the CD133+/CD24+ population werebona fide colorectal CSCs, which also expressed LGR5." (PMID 39822777, 2024). "Furthermore, colon cancer cells, namely, HT29, SW620, and SW837 when treated with dinaciclib showed decreased the expression levels for LGR5, ID1, and CD44v9." (PMID 38182897, 2024). "We and others have shown that anti-LGR5 ADCs are highly effective in inhibiting the growth of LGR5-positive colon cancers in xenograft models without major adverse effects." (PMID 39065640, 2024). "In support of these results, by using ultra-low attachment plates and a specific medium to enrich cancer stem cells, we grow 3D tumourspheres of colon cancer stem cells and find high mRNA levels of CBLL1, LGR5, and c-MYC compared to those levels in 2D monolayer cell cultures." (PMID 38339195, 2024). "Time-lapse live imaging analysis of metastatic cancer cells in the murine primary colon tumors revealed that both Lgr5 positive and negative cancer cells are able to escape from the primary tumors and circulate in the blood stream." (PMID 38659853, 2024). "Moreover, PAF1 knockdown decreased the expression levels of the genes such as LGR5, ID1, ID3, CD44v9, CD133, BMI1, RNF43, EPHB2, SOX9, and ASCL2, which are critical for inducing colon cancer stemness and its markers." (PMID 38182897, 2024). "In the Malmö-CC cohort, we found decreased protein expression of WNT5A in colon cancer tissue in comparison with noncancer colon mucosa, whereas in the same samples, we observed increased LGR5 protein expression." (PMID 37998393, 2023). "We next analyzed in colon cancer cells the expression of LGR5, NANOG, OCT-4, and SOX2 in the presence and absence of α1-PDX." (PMID 35267511, 2022).
colon carcinoma (continued). "Considering our findings above, demonstrating a critical role of de novo FAS for Lgr5+ ISC maintenance and function, we speculated that IEC-specific ACC1 inhibition may also impact on colonic tumor formation." (PMID 35810180, 2022). "To further understand the details of the stem gene expression, we measured the gene expressions of signature stem and self-renewal genes (including OCT4, NANOG, C-Myc, CD133, Lgr5, TGF-β1, and SHP2) of colon cancer in the treated cells with the optimised conditions." (PMID 36612229, 2022). "RSPO1/Lgr5 axis activates Wnt/β-catenin signaling and promotes EMT and tumor formation in breast cancer and glioblastoma whilst, by enhancing TGFβ-mediated growth inhibition and stress-induced apoptosis, it suppresses metastasis in colon cancer." (PMID 35854363, 2022). "Nevertheless, in our study, we found that the suppression of G13D mutation promoted major stem markers like CD133, Lgr5, and TGF-β but not others like CD44 and CD24, which were reported as common and important biomarkers for colon cancer by us and others." (PMID 36386200, 2022). "To establish if the mechanism mediating paracrine cellular communication that we uncovered is conserved in human colon cancer, we then analysed a cohort of 10 human colon tumours (five low-grade adenomas and five invasive carcinomas) for their expression of THBS1, LGR5, and YAP." (PMID 35543624, 2022). "In colon cancer, miR-3120-5p was highly expressed in the population of CD133+ and LGR5+ stem cells." (PMID 34345203, 2021). "We observed increased Srx and Prxs mRNA expression in CSCs sorted using CD133, CD44, and Lgr5 antibodies relative to non-CSCs in several colon cancer cell lines." (PMID 34798428, 2021). "A potential mechanism of these miR-142-3p mimics is the suppression of tumor growth by down-regulating the expression of CD133, leucine-rich repeat containing G protein-coupled receptor 5 (LGR5), and ATP-binding cassette subfamily G member 2 (ABCG2) in colon cancer cells." (PMID 33600577, 2021). "EREG protein expression levels were both detected in LGR5-positive and drug-resistant LGR5-negative colon cancer cells." (PMID 34884633, 2021). "In mice treated with AOM/DSS, the Lgr5+ cells were observed to migrate to the luminal surface after AOM treatment followed by DSS administration, and these were considered to be colon cancer stem cells." (PMID 31947553, 2020). "The human leucine-rich, repeat-containing G protein-coupled receptor 5 (LGR5) is a stem cell marker in numerous adult tissues and is overexpressed in a large number of human carcinoma including colon cancer, breast cancer and oral squamous cell carcinomas (OSCC)." (PMID 30770730, 2019). "Negative LGR5 expression was a significant predictor of peritoneal recurrence in patients with pT4 colon cancer." (PMID 31000786, 2019). "In conclusion, this study revealed that the negative expression of LGR5 in primary tumours is a significant predictor of post-operative peritoneal metastasis in patients with non-metastatic pT4 colon cancer." (PMID 31000786, 2019). "As in the uninfected miR-34a-/- mice, Lgr5-EGFP-CreERT2/miR-34aflox/flox mice did not develop colon tumors spontaneously." (PMID 30543324, 2018). "Consequently, the expression of several β-catenin target genes decreases, including Axin2, Lgr5, Cd44, Birc5, and c-myc, indicating that CCAR1 functions in the same way in gastric cancer cells as it does in colon carcinoma cells." (PMID 28230774, 2017). "Another study has shown that elimination of LGR5+ colon cancer cells prevents liver metastases, but does not inhibit primary tumor growth because of the plasticity of cancer cells within a primary tumor." (PMID 29064439, 2017). "Quantification of LGR5 gene expression in a large cohort of 26 colon adenomas, 137 primary colon carcinomas and 33 liver and lung metastases revealed that approximately two third had LGR5+ patterns and one third had LGR5− patterns compared to normal colon and liver controls." (PMID 26744320, 2016).
colon carcinoma (continued). "Malignant transformation of colon adenomas into primary colon carcinomas and liver metastases resulted in two distinct patterns of LGR5+ or LGR5− in situ signals throughout the malignant epithelia and not the hybrid LGR5+/LGR5− pattern." (PMID 26744320, 2016). "We have recently reported that GATA6 induces the expression of the intestinal stem cell marker LGR5 and enhances the clonogenicity and tumorigenicity of colon cancer cells, but not the growth of these cells cultured under adherent conditions." (PMID 26387746, 2015). "In conclusion, our findings demonstrate that GATA6 simultaneously induces the expression of genes essential for the growth (REG4) and clonogenicity (LGR5), and that cooperation between the GATA6/REG4 and GATA6/LGR5 pathways is important for the tumorigenicity of colon cancer cells." (PMID 26387746, 2015). "Suppression of GATA6 or LGR5 expression attenuates the tumorigenicity of colon cancer cells in nude mice, whereas decreased expression of LGR5, but not GATA6, does not significantly affect the growth of these cells cultured under adherent conditions." (PMID 26387746, 2015). "Previous studies reported that Lgr5 was overexpressed in human colon tumors, as compared to normal colon tissues." (PMID 26674601, 2015). "To further assess Wnt upregulation, we performed qRT-PCR analysis using total RNA isolated from the colonic tumors of APCMin and APC-Cldn1 and detected increased mRNA expression of the established Wnt-target genes CD44 (p = 0.0159), Lgr5 (5-fold increase), and Axin2 (3-fold increase)." (PMID 24997475, 2014). "Importantly, both treatments repressed the direct positive WNT-TCF targetsAXIN2,LGR5, andASCL2 in DLD1 and Ls174T colon cancer cells, although they had variable effects oncMYC (Fig2D)." (PMID 25143352, 2014). "As a further step aiming at the identification of putative cells with the most stemness features, we carried out co-localization experiments with LGR-5, MSI-1, DCAMKL-1 and nuclear β-catenin, an additional putative marker of stemness, especially in colon cancer." (PMID 23374535, 2013). "It is less likely that a known marker for colon cancer stem cells, such as CD44, CD166, EpCAM, and Lgr5, has the potential just like Pten-related pathway in leukemia, which could distinguish hematopoietic stem cells from leukemia-initiating cells." (PMID 19583834, 2009). "Finally, we compared immunostaining of Lgr5 with that of CD133, a previously characterized marker for tumor-initiating cells in colon cancer, and found that they identified distinct subpopulations of cells that were in close proximity, but did not costain." (PMID 19030762, 2008). "Notably, these findings align with prior observations, including the reduced expression of LGR544, EPHB245 and OLFM446 in HG human CRCs; and animal studies which have shown that ablation of LGR5+ cells within colon tumours fails to induce tumour regression." (PMID 40473896, 2025). "Re-expression of RAI2 in human colon cancer cells (HCT116 and LoVo) suppressed the fluorescent activity of Wnt signaling, increased the phosphorylation and inhibited nuclear translocation of β-catenin, with down-regulation of target genes like c-Myc, CyclinD1, ASCL2, and LGR5." (PMID 35299743, 2022). "Importantly, antibody-conjugated drug targeting LGR5 CSCs in colon cancer has no major impact on the function of normal LGR5 stem cells." (PMID 32327656, 2020). "Therefore, it is conceivable to speculate the existence of more proliferative and active LGR5 and CD133 positive CSCs in human colon cancer than the existence of quiescent BMI1 positive cells." (PMID 31057717, 2019). "In conclusion, high mRNA expressions for LGR5, BMI1, TET1 and TET2 in the CD133 and EpCAM positive CSCs may be a useful criterion for better identification of the cells involved in colon cancer in order to specify therapeutic targets against this type of cancer." (PMID 31057717, 2019).
colon carcinoma (continued). "In addition, interconversion of LGR5-positive CSCs to LGR5-negative cells has been shown to facilitate drug resistance in colon cancer." (PMID 29471794, 2018). "However, LGR5 expression in this large group of colon cancer patients did not have prognostic significance." (PMID 29652830, 2018). "However, the effects of these extrinsic agents on colonic leucine-rich repeat-containing G-protein-coupled receptor 5-positive (Lgr5+) stem cells, the cells of origin of colon cancer, have not been documented to date." (PMID 27831561, 2016). "In the absence of KRASmut and LGR5 oncogenic drivers, environmental factors such as chronic inflammation may act to drive colon cancer initiation." (PMID 26744320, 2016). "To identify genes induced by L1 during colon cancer progression whose expression is also elevated in intestinal stem cells, we compared patterns of upregulated gene expression that we obtained from L1-overexpressing Ls174T human CRC cells to those obtained from Lgr5+-mouse intestinal stem cells." (PMID 26399194, 2015). "Our results suggested that the expression of Lgr5 may correspond to the formation and function of Hoechst 33342 low-staining SP cells in colon cancer, and may differentiate these cells from other non-SP cells." (PMID 23153436, 2012). "In a colon cancer xenograft model, EREG was expressed in both LGR5 (an intestinal stem cell marker)-positive and drug-resistant LGR5-negative cells, thereby indicating the involvement of EREG in cancer stemness." (PMID 38398101, 2024). "Preliminary investigations (data not shown) revealed that candidate markers differentially expressed between PC- and Lgr5+-initiated mouse tumors such as DCLK1 and HOXB9 were not equally discriminative among patient-derived colon cancers." (PMID 38902475, 2024). "In this study, we explored a possible relationship between the expression of WNT5A, a favorable prognostic factor in colon cancer, and the β-catenin signaling modulators LGR5 and RSPO3, which are also negative prognostic factors in colon cancer." (PMID 37998393, 2023). "We have recently reported that knockdown of LGR5, in contrast to knockdown of GATA6, does not significantly affect the growth of colon cancer cells cultured under adherent conditions." (PMID 26387746, 2015). "However, no significant negative correlation was detected between miR-363 and LGR5 or REG4 expression ratios (Tumor/Normal) in clinical samples and colon cancer cell lines." (PMID 26387746, 2015). "Moreover, we have recently reported that LGR5 is a transcriptional target of GATA6 and plays important roles in the clonogenicity and tumorigenicity of colon cancer cells, but does not affect their proliferation under adherent conditions." (PMID 26387746, 2015). "In addition, in another public transcript data set (GSE76342) for the colon cancer cell line LoVo with or without metformin treatment, we found that metformin inhibited expression of the CSC markers Lgr5, ASCL2, EPHB3, OLFM4, BMI1, Lrig1, TERT, CD44, and CD133." (PMID 32911743, 2020).
adenoma (106 papers, 2011 to 2025). A neoplasm arising from the epithelium. "By contrast, loss of Apc in Lgr5+ ISCs transformed crypts into β-cateninhi foci that grew into multiple adenomas 4–6 weeks after Cre induction." (PMID 38902475, 2024). "In contrast, loss of Apc in Lgr5+-ISCs transformed crypts into β-cateninhi foci that grew into adenomas 4-6 weeks after Cre induction." (PMID 36711533, 2023). "Paneth cells are progeny of ISCs that provide an epithelial niche for Lgr5+ ISCs in SI, and specific activation of β-catenin signaling in Lgr5+ ISCs is a known cause of adenoma." (PMID 37671945, 2023). "Increased crypt fission also underlies “field cancerization” (the emergence, in the non-dysplastic mucosa, of patches of crypts harbouring pro-oncogenic mutations) as well as the eventual formation of adenomas initiated from mouse APC-deficient Lgr5+ ISCs." (PMID 33673710, 2021). "A number of studies proposed ISC as cells of origin for CRC since activating mutations of the Wnt/β-catenin pathway in LGR5+, Bm1+, or Prom1+ cells lead to adenoma development in mice." (PMID 33916891, 2021). "Consistently, loss of Nedd4 and/or Nedd4l resulted in an increase in Lgr5‐expressing stem cells in the adenomas." (PMID 31867777, 2020). "In genetic mouse models adenomas only appeared when this mutation was specifically introduced in ISCs, for example in in Lgr5+, Bmi1+ or Prom1+ cells, while Apc mutations targeted to the differentiated cells only resulted in indolent cystic structures." (PMID 30927915, 2019). "Thereby, we validated the downregulation of the stem cell markers Smoc2, Lgr5 and Olfm4, as well as the repression of several genes involved in the Wnt/β-catenin signaling and/or Notch signaling in Ap4-deficient adenomas." (PMID 30177706, 2018). "Strikingly, our data revealed an increased formation of cyst-like structures on combined Apc and Bcl-2 loss within the Lgr5+ ISCs at the expense of adenoma formation." (PMID 26956214, 2016). "β-catenin expression also positively correlates with LGR5 over-expression, suggesting the potential involvement of combining LGR5 and β-catenin immunohistochemical markers and degree of expression in the colorectal diagnostic panel for adenoma and carcinoma." (PMID 37512045, 2023). "A study indicated that LGR5+ cell expansion is a hallmark of CRC tumorigenesis occurring during progression to adenoma, which may be related to the change of glandular structure." (PMID 35530362, 2022). "Interestingly, Lgr5, which was up-regulated in Mir34a-deficient adenomas and down-regulated in Csf1r-deficient adenomas, is not only a stem cell marker, but also potentiates Wnt/β-catenin signaling." (PMID 36147476, 2022). "Conversely, APC-deficient Lgr5+ ISCs drive rapid adenoma formation in the mouse small intestine." (PMID 33673710, 2021). "ISC-specific deletion of both adenomatous polyposis coli (APC) alleles using either Bmi1-, CD133-, or LGR5-Cre recombinase mice leads to a rapid full adenoma formation, while a similar APC deletion in late progenitors or differentiated cells only results in sporadic and slow-developing adenoma." (PMID 33916891, 2021). "Furthermore, gene set enrichment analysis (GSEA) showed that mRNAs characteristic for Lgr5-positive ISCs13 were preferentially downregulated in Ap4-deficient adenomas." (PMID 30177706, 2018). "Interestingly, in the presence of constitutive NF-κB activity, a Wnt-activating mutation in the Lgr5-cell is sufficient to induce ‘stemness’ and initiate adenoma formation." (PMID 25635248, 2014). "Similar to the pattern observed in the small intestine of AhCreERT+Apcfl/flBrgfl/fl mice, adenomas in the small intestine of Lgr5-GFP-CreERT2+Apcfl/flBrgfl/fl mice retained Brg1 expression providing further support to the notion that Brg1 loss is incompatible with Wnt-driven adenoma formation." (PMID 25010414, 2014).